INS (insulin)
Diseases named in the same sentence as INS in open-access papers (continued):
Sharing a sentence is not in itself a finding about the gene and the disease.
Hyperglycemia (continued). "Consequently, the role of phosphorylation of Irs1 and Akt in signaling pathways is very crucial in anti-hyperglycemia and insulin sensitivity." (PMID 31736878, 2019). "In particular, T2DM is a chronic and metabolic disease characterised by defects in pancreatic insulin secretion and (or) insulin effect on target tissues, generating a persistent state of hyperglycaemia, inducing metabolic alteration, cell-death and inflammation." (PMID 31398884, 2019). "In βTC3 cells, PON1 induces insulin secretion and ameliorates cell survival, under hyperglycemia." (PMID 31430977, 2019). "However, in the postprandial state, insulin of GDM offspring was significantly increased (p < 0.01), indicating early dysfunction of β cells caused by severe maternal hyperglycemia." (PMID 31340612, 2019). "Notably, there was also a tendency towards more frequent nocturnal hypoglycaemia following RE which warrants acknowledgment when considering the implementation of post exercise insulin dosing strategies to avoid acute hyperglycaemia." (PMID 31428047, 2019). "Our study suggests that hyperglycemia does not exert an immediate toxic effect on podocytes and that other factors, such as exposure to glycated proteins and lack and/or resistance to insulin, are more likely to be the primary cause of podocyte injury." (PMID 30864838, 2019). "There is marked fasting hyperglycemia even in air-exposed KK mice and O3 does not cause any further increases in baseline glucose but does decrease fasting insulin, suggesting impaired insulin release." (PMID 31867021, 2019). "Insulin administration induces hypoglycemia, while glucose alone triggers hyperglycemia." (PMID 31030999, 2019). "Low insulin secretion and modest hyperglycemia are characteristic features of GK rats." (PMID 31131042, 2019). "It would appear that females may be protected against SGA-induced hyperglycemia, and this may be driven by increased insulin secretion (or responses)." (PMID 31555747, 2019). "Interestingly, the hyperglycemia was reversed by week 12, but this was compensated by a robust increase in fasting insulin levels suggesting an induction of insulin resistance." (PMID 31382355, 2019). "Reduction of glucose uptake by insulin-responsive tissues leads to hyperglycaemia." (PMID 31878222, 2019). "Whereas there is still no convincing explanation for the phenomenon of AD connecting with DM, it has resulted in some hypotheses focused on impaired insulin signaling, insulin–resistance in the brain and hyperglycemia-induced excitotoxicity." (PMID 31428627, 2019). "Additionally, proinsulin was found to be insufficiently converted into the mature form, insulin, in islet cells, thus leading to hyperglycemia, in SCG3-knockout mice fed a high-fat/high-sucrose diet." (PMID 31514320, 2019). "Both type 1 and type 2 diabetic patients use insulin for the treatment of hyperglycemia." (PMID 31470605, 2019). "In addition, vitamin E supplementation ameliorated alloxan-induced mouse hyperglycemia by enhancing insulin secretion from the alloxan-treated islets." (PMID 30800211, 2019). "Hyperglycemia impairs insulin signaling that can affect the synthesis and degradation of amyloid-β." (PMID 31461911, 2019). "Therefore, instead of increasing exogenous insulin, we administered other agents to selectively suppress postprandial hyperglycemia." (PMID 30621663, 2019). "The autoimmune destruction of insulin-producing β cells in the Langerhans islets of pancreas results in type 1 diabetes, which is characterized by an insufficient insulin production leading to persistent or recurrent hyperglycemia." (PMID 31295952, 2019). "Indeed, PP hyperglycemia is the result of many interconnected factors, such as the quantity and quality of macronutrients, and the characteristics of insulin regimen; all of which affect both the extent and timing of PP glycemic response." (PMID 31295897, 2019).
Hyperglycemia (continued). "For diabetic dogs, 1 dog was newly diagnosed with DM while the remaining 9 dogs were receiving parenteral insulin and considered to have poorly regulated DM based on persistent clinical signs, results of blood (sustained hyperglycemia) and urinalysis (marked glucosuria) testing." (PMID 31316997, 2019). "In the current study, we chose the time point (2 h post-exercise) based on previous studies on acute exercise, and identified some key DEGs which might contribute to the improvement of hyperglycemia and insulin sensitivity in the exercised GK rats." (PMID 31579613, 2019). "In fructose-fed rats group impaired insulin sensitivity, hypertriglyceridemia, hyperglycemia, hyperinsulinemia, increase in values of protein carbonyl groups (44%), lipid peroxidation (91.3%), a decrease in activities of enzymatic antioxidants, and GSH levels (42.1%) were observed." (PMID 34466478, 2019). "Therefore, our results indicate that there was a compensatory increase in SCG3 formation which enhanced insulin secretion to overcome the hyperglycemia produced by IR." (PMID 31514320, 2019). "In contrast, the downregulated GO terms were related to the response to saccharides, which gave us a hint that the weakened response to glucose in blood may reduce the insulin level, thereby lead to hyperglycemia as previous study reported." (PMID 31632440, 2019). "This picture is further complicated by feedback systems in responsive metabolic systems; hyperglycemia resulting from inhibition of PI3K is corrected through increased insulin secretion which, in turn, activates PI3K/mTOR signaling, reducing the impact of the primary PI3K inhibition." (PMID 31443495, 2019). "Indeed, it is known that insulin sensitizers can ameliorate hyperglycemia, as well as NASH42, although insulin signaling promotes anabolism of lipids." (PMID 30814508, 2019). "EX, with a half-life of more than 2.4 h, only increases insulin release in the case of hyperglycaemia and therefore does not cause hypoglycaemia." (PMID 31526389, 2019). "Additionally, even though our participants were trained on carbohydrate counting, a few pre-exercise bolus insulin under-dosages were observed, contributing to a time spent in hyperglycemia of 17.2% of total time." (PMID 31174360, 2019). "In the meantime, insulin remains an effective, potent glucose-lowering agent with an overall established safety record and is thus considered as part of a combination therapy when hyperglycemia is severe and poorly controlled with the use of oral agents alone." (PMID 31877127, 2019). "In GK rats, hyperglycemia develops as a result of both impaired insulin secretion and action." (PMID 31623226, 2019). "In the TODAY study and in clinical practice, failure of metformin and lifestyle modification often required the initiation of insulin therapy earlier than desired as a means of rapidly improving glycemic control to delay the long-term sequelae of hyperglycemia (nephropathy, neuropathy)." (PMID 31736876, 2019). "The patients experience hyperglycemias that respond poorly to insulin." (PMID 31453022, 2019). "However, dietary supplementation of genistein improved β-cell mass by increasing β-cell proliferation and reducing apoptosis; accordingly, supplementation with genistein alleviated STZ-induced hyperglycemia and improved glucose tolerance and insulin levels." (PMID 30800211, 2019). "However, when the insulin secretory function is insufficient to counterbalance increasing insulin resistance, hyperglycemia appears." (PMID 30678043, 2019). "Besides, we also provide evidences to support that obese Stim-TRiPI flies have hyperglycemia, impairment of insulin signaling in fat body tissue, and larger lipid droplets." (PMID 31061470, 2019). "Additionally, two retrospective observational studies evaluated insulin-based strategies to treat hyperglycemia in hospitalized patients receiving EN." (PMID 31261760, 2019).
Hyperglycemia (continued). "Subsequent work highlighted the efficacy of administering an individualised dose of post-exercise rapid acting insulin in reducing the magnitude and severity of post-exercise hyperglycaemia, without causing early post-exercise hypoglycaemia in those with T1D." (PMID 31428047, 2019). "For example, while its effect on hyperglycemia is minor our data indicate that S100A9 overexpression is able to normalize enhanced hepatic FAO and hyperketonemia and significantly promote survival in different cohorts of insulin deficient mice." (PMID 31391467, 2019). "PPARγ agonists such as PIO function as insulin sensitizers that enhance insulin action, ameliorate hyperglycemia in T2DM, lower plasma free fatty acids and TG, modulate the expression of inflammatory cytokines and prevent excessive lipid accumulation in liver and other peripheral tissues." (PMID 31887984, 2019). "Indeed, we have previously demonstrated that PRAS40 gene therapy with adenoviral vectors improves hepatic insulin sensitivity and reduces systemic hyperglycemia and dyslipidemia in obese mice." (PMID 31728028, 2019). "Post-prandial hyperglycemia is still a challenging issue in intensified insulin therapy." (PMID 31126048, 2019). "A large number of oral antidiabetic drugs, which exert their effects through various mechanisms, aimed at eliminating three major metabolic disorders leading to hyperglycemia: dysfunction of β-cells, peripheral insulin resistance, excessive hepatic glucose production." (PMID 31165274, 2019). "As the main defect in CP-DM is insulin deficiency, for most patients, insulin is the mainstay of treatment and is initiated when oral therapy has not worked or there is uncontrolled hyperglycaemia." (PMID 31687406, 2019). "Due to its seemingly critical role in the liver, this pathway could contribute to the ability of PPARβ/δ agonists to alleviate hyperglycemia and improve insulin sensitivity." (PMID 31121839, 2019). "After acute exercise, the expression of Plin2 was decreased significantly, which might lead to an improvement in insulin sensitivity and hyperglycemia in the exercised GK rats." (PMID 31579613, 2019). "Previous studies showed that Drosophila melanogaster (called Drosophila from now on) fed high-sucrose diets (24–34% sucrose) developed type 2 diabetes-like pathophysiology including increased triacylglycerides, hyperglycemia, and insulin resistance, compared with control diets [5% sucrose,]." (PMID 31091299, 2019). "There are results that hyperglycemia or impaired insulin signaling may be directly involved with the pathophysiology of AD (e.g., tau cleavage and apoptosis) and many reports support that metabolic dysfunction exacerbate the progression of AD in patients." (PMID 31137483, 2019). "The circulating insulin level is elevated with insulin resistance to prevent hyperglycemia." (PMID 30931927, 2019). "Notably, when hyperglycemia is induced in the host body, these xenografts secrete insulin to regulate the blood glucose level in mice for as long as 72 days." (PMID 30937263, 2019). "With this background, we hypothesized that hepatic IRA expression could serve as a glucose uptake facilitator, improving hyperglycemia, one of the main characteristics of insulin-resistant states." (PMID 30642871, 2019). "In addition to inducing insulin resistance, persistent hyperglycemia impairs insulin secretion by pancreatic β-cells." (PMID 31581549, 2019). "As the increase in glucose after an oral glucose challenge is accompanied by an increase in insulin levels, it is unclear whether short-term hyperglycemia or hyperinsulinemia is responsible for the CILP-2 release." (PMID 30896018, 2019). "It is of note that sustained production of macrophage-derived upd3 in response to chronic lipid-rich diet was associated with activation of JAK-STAT signaling, increased fat storage, reduced insulin sensitivity, hyperglycemia, and a shorter lifespan of Drosophila flies." (PMID 30836998, 2019).
Hyperglycemia (continued). "Pancreatic β-cells dysfunction and impairment of insulin action usually leads to hyperglycemia." (PMID 31089370, 2019). "In vivo, FvF improved hyperglycemia and decreased serum insulin level in mice with MetS." (PMID 31547311, 2019). "Moreover, the insulin dysfunction and hyperglycemia in DM induce oxidative stress inhibit coronary nitric oxide generation and increase production of advanced glycation end products (AGEs)." (PMID 31572181, 2019). "It is now an established fact that higher levels of nonesterified fatty acids (NEFA) in the blood can induce preferential use of free fatty acids over glucose to generate ATP even in the presence of insulin in muscle and adipose tissue resulting in hyperglycaemia." (PMID 31007954, 2019). "The development of hyperglycemia was not due to loss of Seriola dumerili insulin- secreting β cells by autoimmunity." (PMID 30899071, 2019). "Insulin alleviates the detrimental effects of hyperglycemia through its metabolic regulation." (PMID 31052277, 2019). "Feeding, insulin and hyperglycaemia inhibit autophagy, prompting the hypothesis that autophagy is prevented when need is greatest in critical illness, leading to accelerated muscle loss." (PMID 30940173, 2019). "Additionally, abnormal lipolysis induces hyperglycemia, reduced insulin secretion, and/or glucose uptake." (PMID 31191707, 2019). "Considering that T2D presents hyperglycemia and hyperinsulinemia, these findings raise the question whether high concentrations of insulin or glucose in vivo are directly responsible for the detrimental actions of NOX2 in endothelial and metabolic function." (PMID 31382355, 2019). "In addition, as insulin is a first-line treatment for diabetic patients with uncontrolled hyperglycemia during the perioperative period, we cannot exclude its potential protective effect during RI/RI." (PMID 31441362, 2019). "Exercise-related hyperglycemia may require a conservative insulin correction dose (50% of usual dose) administered immediately after exercise." (PMID 31258513, 2019). "Indeed, endocrine pancreatic β-islets are responsible for insulin secretion in response to hyperglycemia, therefore contributing to glucose homeostasis." (PMID 31614661, 2019). "The association between simple snoring and hyperglycemia was not significant in our study, but simple snorers showed higher fasting glucose and insulin levels as well as a tendency for higher IR than nonsnorers." (PMID 31093507, 2019). "MAPK signaling mediates the growth factor function of insulin in hyperglycemia." (PMID 30729133, 2019). "Consequent hyperglycemia is requiring lifelong insulin replacement therapy." (PMID 31861649, 2019). "Published data indicate that there might be beneficial effects of bioactive compounds on decreasing hyperglycemia, enhancing insulin secretion, improving β-cell function, decreasing Aβ accumulation, and improving cognitive function in those afflicted." (PMID 30800211, 2019). "SGLT2 inhibitors may be regarded as a major approach of insulin-independent reducing hyperglycemia agents for T2DM treatment." (PMID 31658729, 2019). "Earlier evidence suggested that RebA may reduce hyperglycemia by enhancing insulin secretion and sensitivity." (PMID 31159256, 2019). "The metabolic acidosis was corrected 6 hours after administration of intravenously administered fluid with insulin pump and hyperglycemia was also improved; the insulin pump was discontinued then and switched to subcutaneous insulin 1 day after hospitalization." (PMID 30827279, 2019). "One is ‘feed-forward’ mechanism, as a glucose-induced gene, high expression of BCL11A is triggered by initial hyperglycemia, increased BCL11A inhibits insulin secretion and causes severe hyperglycemia, which further enhance the expression of BCL11A and finally leads to T2D." (PMID 31654056, 2019).
Hyperglycemia (continued). "Results of hyperinsulinaemic–euglycaemic clamp experiments suggest that the subsequent development of hyperglycaemia in iFIRKO mice might be due to reduced hepatic insulin sensitivity of liver, which results in an increased endogenous glucose production." (PMID 31309261, 2019). "In this rat model of hypogonadism, low ghrelin/GH axis might play a role in the elevation of TEE, increased RQ, increased ATGL, hyperglycemia, low insulin, and reductions of food intake and body weight." (PMID 31871453, 2019). "Follistatin and activins may be involved in the regulation of insulin sensitivity and inflammation status (activin A protects against hyperglycemia, hyperinsulinemia, and inflammation)." (PMID 31467615, 2019). "The challenge of producing β cells from pluripotent stem cells faces several inefficiencies including: rate of differentiation, generation of immature insulin producing cells, ethical concern, tumors formation or failure to maintain a sustained correction of hyperglycemia." (PMID 30191384, 2019). "Particular attention was given to the relationship between insulin and glucagon, in an attempt to determine how glucagon may be suppressed during periods of hyperglycemia." (PMID 31829209, 2019). "However, approximately 11% of patients were initially prescribed an insulin, probably reflecting the large number of people with severe hyperglycemia, even among those newly diagnosed." (PMID 30813137, 2019). "Increasing evidence from cell or animal models suggest that bioactive compounds may have direct effects on decreasing hyperglycemia, enhancing insulin secretion, and preventing formation of amyloid plaques." (PMID 30800211, 2019). "The recent studies took into account the effects of some drugs used to treat PD, such as levodopa, which induces both hyperglycemia and hyperinsulinemia, whereas others (including the ergot dopamine agonist bromocriptine) may increase insulin sensitivity." (PMID 31871617, 2019). "We successfully monitored endocrine function in the pancreatic islets by measuring the concentration of insulin in the culture media in response to variable concentrations of glucose, 100 mg/dL (equivalent to normoglycemia) and 450 mg/dL (equivalent to hyperglycemia)." (PMID 31311920, 2019). "Asprosin-dependent high glucose production may also increase glucose toxicity; i.e., hyperglycemia itself disrupts the function of pancreatic insulin-secreting beta cells, thereby increasing insulin resistance." (PMID 31049060, 2019). "The rate of insulin synthesis decreases and leads to a stable hyperglycemia." (PMID 31717650, 2019). "Thus, augmented glucose uptake by inhaled insulin following each meal reduces postprandial hyperglycemia, leading to a reduction in the mean day-long glucose level with reversal of hepatic glucotoxicity." (PMID 31470605, 2019). "In vivo experiments showed that dietary intake of genistein (250 mg·kg−1 diet) improved hyperglycemia, glucose tolerance, and blood insulin level, and increased the number of insulin-positive β-cell in islets, promoted islet β-cell survival, and preserved islet mass in HFD/STZ-induced diabetic mice." (PMID 30823474, 2019). "Attenuation of hyperglycemia was also evident in the intraperitoneal glucose tolerance test, in which neratinib showed lower glucose levels at all time points measured, and enhanced insulin secretion and insulin-to-glucose ratios." (PMID 31676778, 2019). "The rapid increase of plasma FFA can induce insulin resistance and then hyperglycemia." (PMID 31447776, 2019). "In relation to this, our results showed that dietary chokeberry and/or dried jujube fruits may have protective effects against HFFD-related hyperglycemia and insulin sensitivity." (PMID 31171927, 2019). "Here, insulin therapy and rehydration relieved hyperglycemia in patients with hyperglycemic crises." (PMID 30774721, 2019).